ALB (albumin)
Diseases named in the same sentence as ALB in open-access papers (continued):
Sharing a sentence is not in itself a finding about the gene and the disease.
diabetes (continued). "Given the significance of HbA1c, albumin and RDW as biomarkers in diabetes, exploring the correlations between these parameters might provide deeper insights into the disease’s pathophysiology and its complications." (PMID 39125606, 2024). "Several variables weresignificantly different, including sex, age, drinking, smoking, diabetes history,Cr, UA, HbA1c, TG, HDL-C, lymphocyte, albumin, CRP, angiotensin-converting enzymeinhibitor (ACEI), angiotensin receptor blocker (ARB), and proton pump inhibitors(PPI) (all p < 0.05)." (PMID 39076545, 2024). "Mildly increased urine albumin excretion (microalbuminuria) is typically observed at an early stage of DN in human type 1 diabetes and was, as expected, evident in mice with STZ-induced diabetes at both time-points studied." (PMID 38443965, 2024). "The differences in age, gender, history of diabetes, cause of sepsis, hemoglobin, WBC, blood sugar, and albumin were not significant between CIP patients and non-CIP patients." (PMID 39109270, 2024). "Factors selected in the multivariable logistic regression analysis were age, sex, smoking, alcohol abuse, diabetes, size of the hematoma, hematoma clearance operation, size of the hematoma, intraventricular hematoma, GCS, leukocyte, lymphocyte, albumin, and platelets (shown in eTable 1)." (PMID 38404841, 2024). "Patient data, including age, diabetes history, liver cancer, hepatic artery embolization, recent antibiotic use, invasive procedures within two weeks, APACHE II Scoring, ALB and SAA and BLA levels, were compared between the sepsis and non-sepsis groups, showing significant differences (P < 0.05)." (PMID 39039452, 2024). "Additionally, the authors suggested that the LSM was related to the duration of diabetes, ALT level, urinary albumin/creatinine ratio, and HDL-C level." (PMID 39775020, 2024). "We found that serum albumin was negatively linked to BEOC in women younger than 40, non-Hispanic Whites with low PIR, non-smokers, and people who did not have COPD, cancer, diabetes, liver disease, or use steroid." (PMID 38835754, 2024). "The results showed that 17 variables, including BMI, DBP, neutrophil count, albumin, serum creatinine, eGFR, serum cystatin C, triglycerides, serum IgG, serum C3, UPE, hematuria, CKD stage, nephrotic syndrome, diabetes, T, and C, were statistically significant factors (P < 0.05)." (PMID 39494280, 2024). "These factors include age, smoking, hypertension, diabetes, coma (GCS<8), ASA physical status, emergency surgery, postoperative hemoglobin, postoperative albumin, duration of ventilation, blood transfusion, surgical duration, unplanned re-operation, surgical incision, and deep vein catheterization." (PMID 39776439, 2024). "Significant differences were observed in age, diabetes history, history of liver cancer, history of hepatic artery embolization, recent antibiotic exposure, invasive procedures in the last 2 weeks, APACHE II Scoring, and ALB, SAA and BLA levels." (PMID 39039452, 2024). "The hub gene identified in our study in the SOY1.5 group, that correlates with albumin, is CCL5 (RANTES) in diabetes-related renal pathophysiology, and serum albumin may play a relevant role." (PMID 39021677, 2024). "Following the establishment of a longitudinal association between ABG and 30-day mortality in ADHF patients, mediation models were used to analyze the effects of WBC, GGT, and ALB in mediating this relationship in patients with and without diabetes." (PMID 39036046, 2024). "Our study demonstrated that circulating TFAs are positively and independently correlated with urinary albumin excretion, especially among participants with hypertension or without diabetes." (PMID 37710270, 2023). "Age, BMI, diabetes mellitus prevalence, eGFR, M2BPGi, liver functional reserve-related factors (Child–Pugh class B/C, MELD score, albumin, and PT–INR), and sarcopenia-related factors (SMI, hand grip strength, and gait speed) significantly differed between the three groups." (PMID 37780552, 2023).
diabetes (continued). "The immunoturbidimetric method used has been reported to be unable to detect albumin molecules with altered conformation, which may be produced in people with CKD and diabetes." (PMID 37755765, 2023). "A negative relationship with BP control was found with diabetes, obesity, the metabolic syndrome, urinary albumin excretion, high pulse pressure, and lack of antihypertensive treatment." (PMID 38173815, 2023). "In contrast, Another study showed that T cell-positive patients had a shorter duration of diabetes and lower albumin excretion rates than T cell-negative patients." (PMID 36776877, 2023). "Fasting blood glucose, the albumin-creatinine ratio (ACR), serum creatinine levels, and serum blood urine nitrogen (BUN) levels are the most used biochemical parameters to estimate the progression of renal disease and diabetes control." (PMID 36901874, 2023). "An increased fraction of oxidized relative vs. non-oxidized albumin is also characteristic of Diabetes Mellitus patients." (PMID 37926735, 2023). "Compared to the lowest VAI group, participants with increased VAI group were significantly more likely to have hypertension, diabetes, elevated BMI, serum uric acid, total cholesterol, ALT, AST, waist circumference, TGs, urinary albumin, ACR and decreased HDL-C levels (all P < 0.05)." (PMID 36969806, 2023). "Urinary albumin excretion and blood pressure were not further increased by diabetes induction, while heart weight was higher in the MWF-D." (PMID 38069331, 2023). "We aim to analyse the prognosis of elevated urine albumin creatinine ratio (uACR) in the CAD population with or without type 2 diabetes mellitus (T2DM)." (PMID 37563647, 2023). "In this study, we observed an increase in glomerular Ps’alb following diabetes onset that was reduced by MR antagonism measured using an ex vivo assay independent of hemodynamic factors and tubular albumin reuptake." (PMID 36749631, 2023). "In addition, gender, marital status, alcohol drinking status, smoking status, hypertension, diabetes, uric acid, glycohemoglobin, fasting glucose, HDL-C, total cholesterol, triglycerides, LDL-C, and albumin were significantly different between the two groups." (PMID 37559054, 2023). "Univariate analysis revealed 19 significant variables, including diabetes mellitus, history of biliary surgery, abdominal effusion, RBC, HGB, IBIL, TP, ALB, BMI, WBC, percentage of neutrophils, neutrophil absolute value, ALT, AST, ALP, TBIL, CA, and CREA (P < .05)." (PMID 38013294, 2023). "However, the association remained significant after adjusting for BMI, serum albumin, CRP and comorbidity of diabetes and cardiovascular diseases." (PMID 37696942, 2023). "Moreover, in people with diabetes, adherence to annual screening for DKD with estimated glomerular filtration rate (eGFR) and urine albumin-creatinine ratio (UACR) remains a challenge." (PMID 37706530, 2023). "In the present real-world series, it turns out that the most relevant parameters predicting success and survival in major salvage surgery of the larynx are not cancer-related but patient-related parameters (diabetes and postoperative albumin levels)." (PMID 37623473, 2023). "In our data, urine-albumin creatinine ratio results were not available for patients without diabetes, so we relied solely on eGFR to define CKD, thus characterizing patients with normal eGFR but with microalbuminuria or macroalbuminuria as free of CKD." (PMID 37461134, 2023). "Urine albumin or albuminuria is one of the most important biomarkers of kidney damage in individuals with or without diabetes." (PMID 36926036, 2023). "Our study demonstrated that TFA isoforms were positively and independently correlated with urinary albumin excretion, especially in participants with hypertension and without diabetes." (PMID 37710270, 2023). "Age, sex, BMI, preoperative serum albumin level, history of diabetes mellitus, pancreatic disease, and tumor location did not significantly differ between the two groups." (PMID 37046241, 2023).
diabetes (continued). "Collectively, these findings suggest that it is necessary to carefully monitor for increased urinary albumin excretion in individuals with high levels of circulating TFAs, particularly those with hypertension and those without diabetes." (PMID 37710270, 2023). "Significant differences were also observed in blood lipids (triglycerides and cholesterol) between the two groups, as well as higher serum creatinine and urinary albumin to creatinine ratio (ACR), with >30% of the participants in the diabetes group exhibiting microalbuminuria (i.e., ACR > 30 mg/g)." (PMID 37891943, 2023). "The two groups displayed significant differences in clinical data such as age, sex, educational level, hypertension, current drinker, SBP, DBP, height, BMI, WC, duration of diabetes, FPG, HbA1c, hemoglobin, leukocytes, gamma-glutamyl transferase, ALB, TG, TC, hs-CRP, ACR, and eGFR." (PMID 37645414, 2023). "Blood pressure control was lower in hypertensive patients with diabetes, obesity, the metabolic syndrome, increased urinary albumin excretion, higher pulse pressure, and lack of antihypertensive treatment." (PMID 38173815, 2023). "Age, gender, body mass index, ASA physical status score, medical illness (hypertension or diabetes mellitus), neoadjuvant therapy, and preoperative albumin were not significantly different between the two groups." (PMID 36755252, 2023). "We refer interested readers to this work, in which univariable associations with frailty were observed for diabetes, cardiovascular conditions, peripheral vascular disease (PVD), serum albumin, and serum bicarbonate (but not for hemoglobin or Kt/V)." (PMID 37675341, 2023). "Glycated albumin (GA) has recently been proposed as a screening marker for diabetes among non-pregnant individuals." (PMID 37932245, 2023). "A previous study in 2022 showed that only 9% of American veterans with hypertension who did not know CKD or diabetes had prior urine albumin/creatinine ratio measure." (PMID 36844731, 2023). "Models to generate LS means are adjusted for age, sex, education, race and ethnicity, BMI, estimated GFR, systolic and diastolic blood pressure (BP), triglyceride, HDL, LDL, diabetes, hypertension, statin use, CVD history, smoking status, heart rate, first PWV measure, and urine albumin." (PMID 37181121, 2023). "Prior studies indicated a negative correlation between albumin levels and the incidence of diabetes." (PMID 38111710, 2023). "As anticipated, both the albumin-to-creatinine ratio (ACR) and estimated glomerular filtration rate (eGFR) were significantly higher in the diabetic nephropathy (DN) group than in the diabetes (DM) group." (PMID 37513479, 2023). "Insulin therapy has for many years remained the gold standard in controlling diabetes, but it has also proven effective in reducing urine albumin excretion and does not negatively hinder kidney function as it is cleared by the kidneys." (PMID 37090383, 2023). "Additional one by one adjustments for serum albumin, diabetes, CVD, or treatment with dialysis did not change the estimated risk substantially." (PMID 37181128, 2023). "Patients with higher age, lower HCT, lower albumin, lower CREAT, higher CRP, lower NPCR, higher IDWG, higher ferritin, higher phosphorous, higher WBC, presence of diabetes, lower potassium, lower BMI, low RRF, and lower pre and post weight have a higher chance of mortality in the following 3 years." (PMID 36403633, 2023). "In this study, the beneficial effect of LPD–KAs on kidney function was persistent after stratification by diabetes status without any impairment in nutritional status measured by serum albumin levels." (PMID 37726370, 2023). "The significant correlation between the red cell distribution width/albumin ratio and proteinuria indicates its potential as a non-invasive marker for renal dysfunction in diabetes." (PMID 37791152, 2023).
diabetes (continued). "Meanwhile, the urine albumin/creatinine ratio was remarkably reduced in diabetes patients who were treated with RES (500 mg/day) for 90 days, suggesting that RES may be protective against DKD by reducing urinary albumin excretion." (PMID 37308949, 2023). "In the group without diabetes, the average value of albumin was 35.3 g/L, showing that metabolic disorders were already present (p < 0.001)." (PMID 37627906, 2023). "Regarding the APD group, among patients with normal albumin levels, 60.71% (N = 17) had no history of diabetes compared to 39.29% (N = 11) who were diabetic." (PMID 38021540, 2023). "In patients with type 1 diabetes mellitus, reduced SEVR values correlate independently and negatively with the presence and degree of microalbuminuria and are a superior predictor of PWV in assessing the albumin excretion rate." (PMID 36676648, 2022). "Current guidelines recommend that an increase in urine albumin/creatinine ratio (UACR) and decrease in estimated glomerular filtration rate (e-GFR) in diabetes patients could be an important predictor of the occurrence and development of DKD." (PMID 36614886, 2022). "According to the Japanese Diabetes Society, values of GA in non-diabetic patients should range within 11–16%, normalized to the total albumin, whereas diabetic patients generally exhibit values greater than 20%." (PMID 36140073, 2022). "uEV were then divided based on the urinary albumin level into the following groups: diabetes patients with normoalbuminuria (NAlb DN), patients with microalbuminuria (MiAlb DN) and patients with macroalbuminuria (MaAlb DN)." (PMID 36292960, 2022). "The selected variables include pre-operative delirium, CVA with the modified Rankin scale, age, CCI, random glucose levels of patients with diabetes, application of benzodiazepines in surgery, surgical delay, creatine level, active smoker, general anesthesia, serum BUN level, and albumin level." (PMID 36061065, 2022). "Moreover, they had higher waist (p = 0.003), diabetes duration (p < 0.001), sBP (p < 0.001), HDL-cholesterol (p = 0.021), and albumin/creatinine ratio (p < 0.001)." (PMID 36407461, 2022). "Patients in the high PLT group had a higher rate of diabetes and higher levels of BMI, neutrophil, lymphocyte, hemoglobin, cholesterol, triglycerides, RRF, and calcium, but lower serum urea nitrogen, creatinine, albumin, and phosphorus." (PMID 36285366, 2022). "This association remained significant in extended model 2 additionally adjusted for serum albumin, LDL cholesterol, smoking status, diabetes mellitus, statin use, triglycerides, BMI, systolic and diastolic blood pressure and CVD at baseline (HR = 0.81, 95% CI 0.73–0.89, p = 0.00004)." (PMID 34914850, 2022). "Glycated albumin (GA) is a potential biomarker for diabetes because it is not influenced by the erythrocyte life span." (PMID 35942243, 2022). "After adjustment for time-dependent age and dialysis vintage, gender, diabetes, TAWG, and serum albumin, patients with pre-dialysis hyponatremia based on TASNa (HR 2.33; 95% CI 1.16–4.68; model 3) had a higher risk of new MACE compared with those with normonatremia." (PMID 35780279, 2022). "More CKD patients with diabetes versus those without diabetes had their albumin-to-creatinine ratio (ACR) assessed (64.2 vs. 17.0%) or received an ACE inhibitor/ARB (78.3 vs. 58.1%) or statins (64.6 vs. 39.2%)." (PMID 35583597, 2022). "The five parameters, TG, TC, HDL-C, LDL-C, and Non-HDL-C had positive non-linear dependent relationships with [Ca2+]corr after adjusting for gender, age, waist circumference, BMI, SBP, DBP, a diabetes diagnosis, lymphocytes, basophils, RBC, MPV, FSG, albumin, uric acid, and ALT (all P < 0.05)." (PMID 35872922, 2022). "Consistent with previous studies, serum albumin and pre-albumin are lower in sarcopenia than in the non-sarcopenia group, but not sex, BMI, dialysis duration, diabetes, and Hs-CRP." (PMID 36458164, 2022).
diabetes (continued). "Blood pressure, heart rate, urine albumin excretion and body weight were higher in patients with than without diabetes." (PMID 35057807, 2022). "Among three SII tertiles, differences with statistical significance were observed in age, gender, race, smoking status, physical activity, BMI, SBP, DBP, diabetes, hypertension, SCr, total cholesterol, HDL-C, ALT, AST, waist circumference, triglycerides, eGFR, urinary albumin, and ACR (all p<0.05)." (PMID 35386695, 2022). "After adjusting for age, sex, BMI, smoking habits, serum albumin, and hsCRP, patients with T2D had a significantly higher odds ratio (OR) of disease progression in periodontitis than did those without diabetes (OR = 1.64, 95% CI: 1.02–2.65, p = 0.04)." (PMID 35522619, 2022). "In the early stage of diabetes, tubular albuminuria was reported without changes in glomerular albumin permeability and eGFR." (PMID 36430671, 2022). "With the elevation of testosterone quartiles, male subjects were older and had higher AST/ALT and HDL-C, lower morbidity of hypertension and dyslipidemia, platelet count, albumin, BMI, waist circumference, FPG, blood pressure and triglycerides, and a longer duration of diabetes." (PMID 36572925, 2022). "Therefore, our results suggest that on-admission albumin levels may be a predictor for all types of hospitalized COVID-19 patients, and that this was independent of other variables such as age, hypertension, dyslipidemia, active cancer, diabetes mellitus, COPD and glucose levels." (PMID 35160039, 2022). "This association was significant regardless of age, gender, diabetes, BMI, SBP, hemoglobin, serum albumin, eGFR, urinary sodium excretion, and urinary protein excretion." (PMID 35284436, 2022). "Additionally, after adjusting for DBP, duration of diabetes, HbA1c, hemoglobin, ALT, AST, GGT, albumin, BUN, TC, LDL-C, statin use and metformin use, the RCS curves also demonstrated a positive correlation between CVAI and the presence of MAFLD." (PMID 35979441, 2022). "We further had no information on hypertension, diabetes, alcohol use and nutritional status such as albumin, and were hence unable to include these potential factors in our models." (PMID 35831837, 2022). "On the other hand, the correlation between blood VD and age, refractive power, diabetes course, fasting blood glucose, glycosylated hemoglobin, and serum albumin were not statistically significant (all p > 0.05)." (PMID 36474199, 2022). "In addition to tumor size > 6.5 cm, age ≥ 65 years, histological cirrhosis, diabetes mellitus, chronic HCV infection, hemoglobin ≤ 10 g/dL, and albumin ≤ 3.5 g/dL were found to be related to tumor recurrence after liver resection for T1 HCC (all p < 0.05)." (PMID 36169915, 2022). "Recent clinical studies have found that uric acid-lowering therapy (such as allopurinol) could reduce urinary albumin excretion rates (UAER) and Scr, increase eGFR, and thus reduce kidney damage in patients with diabetes." (PMID 35856157, 2022). "Age, sex, DBP, SBP, BMI, neck circumference, waist circumference, hypertension, duration of diabetes, CCA plaque, FPG, HbA1c, hemoglobin, erythrocyte, leukocyte, γ-GT, albumin, urea nitrogen, uric acid, triglyceride, hs-CRP, UACR and eGFR were significantly different between the two groups." (PMID 35784528, 2022). "Glycated albumin initially increased through Week 4 in both subgroups before stabilizing at approximately 20% in the Diabetes subgroup and approximately 17% in the No Diabetes subgroup." (PMID 35462610, 2022). "There has never been any research on the management of diabetes mellitus from the standpoint of albumin and ASX, as well as ASX-metal ions." (PMID 35563162, 2022). "These cohort studies had 13 risk factors, including age, sex, body mass index (BMI), smoking, diabetes duration, fasting plasma glucose (FBG), hypertension, HbA1c, albuminuria, eGFR, urine albumin:creatinine ratio (UACR), total cholesterol (TC), and triglyceride (TG)." (PMID 35360073, 2022).